HGF (hepatocyte growth factor)
Diseases named in the same sentence as HGF in open-access papers (continued):
Sharing a sentence is not in itself a finding about the gene and the disease.
cancer (continued). "In turn, when co-cultured with c-Met expressing cells, ASCs expressed higher levels of the mitogen HGF, thus suggesting a double ASCs-cancer cell crosstalk mediated through HGF/c-Met signaling." (PMID 33916703, 2021). "Hepatocyte growth factor (HGF) production by stromal fibroblasts can also drive the activation of MAPK/ERK signalling in cancer cells, which can reduce the efficacy of targeted therapy." (PMID 34298736, 2021). "The top three growth factors with strong correlations with OSM in most cancers were HGF, PDGFB, and TGFB1." (PMID 34702277, 2021). "Metastasis-associated colon cancer gene-1 (MACC1) was first described as a c-MET transcription regulator that mediates cancer colon progression and metastasis by its ligand hepatocyte growth factor (HGF)." (PMID 34577857, 2021). "Cancer-associated fibroblasts (CAFs) can produce epidermal growth factor (EGF), hepatocyte growth factor (HGF), fibroblast growth factor (FGF), IL-6, IL-8, chemokine C-X-C motif ligand 12 (CXCL12), and matrix metalloproteases (MMP-3 and MMP-9)." (PMID 33406763, 2021). "This system fullfills the requirement for MET activation in conditions of expedience, and allows to evaluate the contribution of the HGF/MET axis to the dissemination of human cancer cells." (PMID 33446252, 2021). "Previous studies represented to present that overexpression of HGF/cMet inhibited apoptosis in cancer cells via modulating mitochondrial proteins." (PMID 34683124, 2021). "Functionally, paracrine HGF from PSCs can activate the c-Met/PI3K/Akt pathway in cancer cells, leading to inhibition of cancer cell apoptosis and induction of chemoresistance to gemcitabine." (PMID 33546284, 2021). "More recently, TME cytokines, such as IL-6 and HGF, were demonstrated to have clinical relevance and induce cancer cell stemness concomitantly enhancing the epithelial-to-mesenchymal transition (EMT), cell migration, and metastatic potential." (PMID 34408135, 2021). "Subsequently, HGF was found to be involved in cancer invasion and metastasis in a variety of solid tumors and was associated with poor prognosis." (PMID 34777462, 2021). "Among them, transforming growth factor beta (TGF-β) and hepatocyte growth factor (HGF) are particularly relevant in the progression of carcinomas to bone metastasis." (PMID 34572548, 2021). "HGF, as a stromal factor, finds its receptor Met on carcinoma cells and on osteoblasts and osteoclasts." (PMID 34572548, 2021). "Both the HGF-activator-mediated and matriptase-mediated mechanisms are proposed to be involved in the processing of scHGF into tcHGF in cancer tissues." (PMID 33121208, 2020). "Constitutional NF-κB activation in cancer cells enhances the level of growth factor genes such as hepatocyte growth factor (HGF), BMP, and granulocyte colony-stimulating factor (G-CSF)." (PMID 32149326, 2020). "The HGF/c-Met signaling pathway affects multiple cellular processes during cancer progression, including cell proliferation, migration, invasion, apoptosis, and drug-resistance." (PMID 33425885, 2020). "This study highlighted the importance of the interaction between ncRNAs and HGF/c-Met axis in cancer development and therapy." (PMID 32083078, 2020). "Our in vitro data with the 3D model indicated that HGF + c-MET inhibition significantly reduces cancer cell stemness (as assessed by ALDH-1 expression)." (PMID 32203220, 2020). "Numerous reports in the literature demonstrate great importance of HGF in the pathogenesis of cancer, including intracranial tumors." (PMID 32607415, 2020). "To investigate if all these expression changes of glycolysis and cancer-relevant genes upon HGF stimulation led to changes in glucose metabolism in Detroit 562, we performed extracellular flux assays (glycolytic rate assays)." (PMID 31940827, 2020). "Functional in vitro assays with purified MDSCs revealed that the TGF-β, epidermal growth factor (EGF) and HGF signaling pathways were all involved in MDSC-induced EMT activation of cancer cells." (PMID 35582229, 2020).
cancer (continued). "MET is a receptor for hepatocyte growth factor (HGF), and its overexpression is related to the process of metastatic dissemination and drug resistance in several cancers, resulting in poor prognosis." (PMID 32486306, 2020). "Dysregulation of the HGF-c-Met signaling pathway has been implicated in the onset, progression and metastasis of various cancers, making the HGF-c-Met axis a promising therapeutic target." (PMID 32626713, 2020). "Based on current progress, this review summarizes the current challenges and simultaneously proposes future opportunities for HGF/MET targeting for therapeutic cancer interventions." (PMID 32435640, 2020). "We recently identified a novel population of highly cytotoxic c-Met-expressing CD8+ T lymphocytes and found that hepatocyte growth factor (HGF) limits effective murine cytotoxic T cell responses in cancer models." (PMID 32075650, 2020). "Our findings clearly indicate that it is the triple therapy (the combination of a chemotherapeutic agent with compounds that inhibit both arms of HGF/c-MET pathway) that gives the best outcomes in terms of preventing cancer progression." (PMID 32203220, 2020). "In this study, we investigated the mechanism underlying the anti-cancer effects of cabozantinib through the regulation of GAS6-AXL and HGF-MET signaling." (PMID 32055714, 2020). "Further mechanistic studies showed that hepatocyte growth factor/c-Met pathway was activated in cancer stem cell enrichment and responsible for the cir-CCDC66 upregulation." (PMID 31994979, 2020). "Antagonists of the HGF/cMET pathway have been developed and are being tested in multiple types of human cancer." (PMID 32983165, 2020). "HGF/MET regulates epithelial to mesenchymal transition (EMT) in normal physiology as well as during cancer progression." (PMID 32722184, 2020). "We are the first to indicate that the depletion of SAAL1 affected the characteristics of cancer aggressiveness and inhibited the HGF/Met-driven Akt/mTOR signaling pathway." (PMID 32650537, 2020). "HGF also increases permeability between vascular endothelial cells and promotes movement of cancer cells across the endothelial cell barrier into the adjacent tissues." (PMID 33271944, 2020). "Once HGF binds to c-MET on cancer cells, uPA production by cancer cells is induced, leading to activation of more pro-HGF to active HGF." (PMID 33271944, 2020). "In this review, the crosstalk between the HGF/c-Met axis and ncRNAs (mostly miRNAs and lncRNAs) in common human cancers are summarized." (PMID 32083078, 2020). "HGF is a pleiotropic growth factor and a key mediator of cell migration/invasion, proliferation, and survival/apoptosis in cancer cells via activation of its receptor, c-Met43." (PMID 32807808, 2020). "ASCs secrete factors that are potentially associated with cancer development and progression, including IGF-1, transforming growth factor beta 1 (TGFβ1), vascular endothelial growth factor (VEGF), hepatocyte growth factor (HGF), and IL-8." (PMID 33105727, 2020). "C-Met is aberrantly activated by gene amplification, overexpression, mutation, binding to other ligands, autocrine signaling or abnormally high HGF levels in cancer." (PMID 32117981, 2020). "The definition of “higher” pretreatment HGF is relative and is likely dependent upon the patient cohort treated and the cancer subtype." (PMID 32695883, 2020). "As a co-receptor, neuropilin-1 modulates the activity of various ligands such as VEGF, TGF-β, HGF, or semaphorins, which promotes cancer growth, angiogenesis, and metastasis in various types of cancer." (PMID 32388640, 2020). "We have previously shown that mitogen-activated protein kinase (MAPK) and phosphatidylinositol 3-kinase (PI3K) are the major downstream signalling molecules that mediate HGF-induced proliferation and migration of cancer and endothelial cells." (PMID 32203220, 2020).
cancer (continued). "MET inhibitors reduce proliferation, invasion, migration, and downstream signalling in gastric MET-amplified cancer cells, but overexpression of HGF in cancer cells impairs this phenomenon." (PMID 33271944, 2020). "For example, neutrophils-mediated cancer cell killing is dependent on hepatocyte growth factor (HGF)/MET-induced nitric oxide release." (PMID 33101283, 2020). "The strict regulation of HGF/c-Met signal transduction, observed in growth and regeneration, results in different degrees of maladjustment in various cancers, especially in the case of drug resistance or metastasis." (PMID 33195182, 2020). "As shown in different cancer models, hepatocyte growth factor/mesenchymal–epithelial transition (HGF/Met) signaling contributes to an immunosuppressive microenvironment." (PMID 33233528, 2020). "We studied the interactions of MET and EGFR upon stimulation by HGF or EGF in the two cancer cell lines, HeLa and BT-20, which exhibit inverse MET:EGFR expression ratios." (PMID 32316583, 2020). "Michieli and colleagues showed that the transforming potential displayed by mutant forms of MET found in human cancer is sensitive to, and can be entirely dependent on, the availability of the ligand HGF." (PMID 33271944, 2020). "Numerous studies have indicated that abnormal activation of the HGF/c-Met signaling pathway can lead to cell proliferation, invasiveness, and metastasis of cancers of the digestive system." (PMID 33195182, 2020). "Multiple therapeutic agents that target the hepatocyte growth factor (HGF)–MET pathway in these cancers are under development." (PMID 33178590, 2020). "HGF can also be secreted by the cancer cells themselves and exert its effect in an autonomous manner to regulate the expression of its own receptor in a MITF-dependent manner." (PMID 33276788, 2020). "While HGF/MET in normal cells acts in a paracrine manner, HGF/MET signaling in cancer cells is often autocrine-mediated." (PMID 33066121, 2020). "Numerous in vivo and in vitro studies have demonstrated that HGF/c-Met play a critical role in the development of various human cancers (renal, lung, liver, breast, colon, thyroid, ovarian, and pancreas)." (PMID 32117981, 2020). "Hepatocyte growth factor (HGF) known as a multifunctional growth factor that upregulates cancer cell motility, invasiveness, proliferative, and anti-apoptotic activities through phosphorylation of MET (a specific receptor of HGF)." (PMID 32290402, 2020). "Since then, the role of HGF/MET in cancer invasion has been demonstrated in a variety of cancer cells." (PMID 33066121, 2020). "Abnormal c-MET signaling has been demonstrated in a number of human cancers as a result of c-MET receptor overexpression, receptor mutation or amplification, HGF overexpression or the formation of abnormal autocrine signaling." (PMID 32117721, 2020). "Many studies have revealed that ncRNAs play a crucial role in cancer initiation and progression by regulating different downstream genes or signal transduction pathways, including HGF/c-Met axis." (PMID 32083078, 2020). "Patients with advanced CRC have elevated serum HGF at diagnosis and decreased levels after cancer resection." (PMID 32296018, 2020). "Apte’s team revealed that PSC-secreted HGF enhanced the aggressiveness of PDAC via its receptor c-MET on cancer cells, and HGF inhibition resulted in a significant reduction of metastasis in mouse models of PDAC." (PMID 33520728, 2020). "MET activation by HGF also leads to the activation of pathways that regulate epithelial–mesenchymal transition (EMT), a hallmark of cancer progression." (PMID 33066121, 2020). "In cancer cells, HGF/MET are often overexpressed, and this overexpression is found to correlate with tumorigenesis, metastasis, and poorer overall prognosis." (PMID 33066121, 2020). "According to Mizuno and Nakamura, stroma-secreted HGF is required for cancer cells to infiltrate neighboring tissues, such as vascular beds, across the basement membrane." (PMID 33066121, 2020).
cancer (continued). "Overactivation (induced by increased HGF-activating TTSPs or decreased HAIs) revealed cancer progression through MET phosphorylation." (PMID 32290402, 2020). "The serine peptidase inhibitor Kunitz type 2 (SPINT2), a Caco-2 line-specific EV protein, inhibits HGF and suppresses the progression of various types of cancer." (PMID 32916986, 2020). "The activation of c-MET by HGF is well-known to induce cells viability and proliferation in many kinds of cancer cells." (PMID 32545325, 2020). "Previous studies showed that the hepatocyte growth factor (HGF)–Met receptor axis plays long-lasting cardioprotection against doxorubicin anti-cancer therapy." (PMID 32722178, 2020). "Gemcitabine alone or in dual or triple combinations with HGF/c-MET inhibition significantly reduced proliferating cancer cells compared with the rest of treatments." (PMID 32203220, 2020). "MAPK signaling pathway, pathway in cancer, and toll like receptor signaling pathway, and so on, were enriched in HGF and c-MET high expression phenotype." (PMID 32788873, 2020). "Using cell-mediated cytotoxicity reactions in vitro and in vivo, we demonstrated also that the c-Met receptor ligand HGF can directly negatively regulate c-Met+ CTL cytolytic function in a cancer model." (PMID 32075650, 2020). "Cancer cells stimulate the expression of hepatocyte growth factor (HGF) in CAFs through secreting platelet-derived growth factor, IL-1 and basic fibroblast growth factor." (PMID 32499786, 2020). "Treatment with HGF-neutralising antibody + c-MET inhibitor (Hi + Ci), as well as gemcitabine in combination with HGF/c-MET inhibition (Hi + Ci + G) significantly increased apoptosis of cancer cells." (PMID 32203220, 2020). "Activation of HGF/MET signaling axis in cancer cells also plays a significant role in proliferation, angiogenesis, epithelial-mesenchymal transition (EMT), and drug resistance." (PMID 32290402, 2020). "Genetic alternations and overexpression of MET are broadly observed in various cancer types such as lung cancer, breast cancer and glioblastoma, and abnormal activation of HGF-MET signaling is involved in tumor progression and metastasis." (PMID 32055714, 2020). "Accumulating knowledge of the close relationship between cancer and the HGF-MET pathway identifies it as a highly promising site for targeted therapy." (PMID 32296018, 2020). "Hepatocyte growth factor (HGF): HGF-mediated c-MET signalling is observed in cancer with its expression correlating with that of HS." (PMID 33256730, 2020). "HGF produced by osteoblasts has been validated to induce migration of cancer cells from sinusoidal capillaries to bone marrow space and stimulates growth of cancer cells in the bone microenvironment." (PMID 31897234, 2020). "Matriptase is highly expressed in CRC patient samples and in CRC cell lines, including those used for this study, which makes it plausible that matriptase is the major activator of pro-HGF in this cancer type." (PMID 32807808, 2020). "The results of this study clearly identified MET signaling as an additional auto- and paracrine survival pathway in cancer cells that can be induced and sustained by HGF secretion from perishing stromal cells." (PMID 32485915, 2020). "In this review, we summarize advanced development of clinical research on HGF/c-Met antibody and small-molecule c-Met inhibitors of cancers of the digestive system and provide a possible direction for future research." (PMID 33195182, 2020). "Growth arrest-specific 6 (GAS6) and hepatocyte growth factor (HGF), the natural ligands of AXL and MET, respectively, are associated with the induction of cancer cell proliferation or metastasis." (PMID 32055714, 2020). "It is well known that HGF/c-Met system regulates, in other organs, both embryonic development and cancer progression." (PMID 30646583, 2019).
cancer (continued). "The HGF/c-MET axis especially affects the migration of cancer cells from the primary site to other organs by promoting epithelial-mesenchymal transition (EMT), which initiates cancer cell metastasis." (PMID 31355133, 2019). "A recent study demonstrated that the glycolytic switch in HNSCC cancer cells is induced by CAF-derived HGF and in turn HNSCC-secreted bFGF promotes lactate consumption by CAFs." (PMID 30927923, 2019). "Altogether, these findings suggest that Nrf2 is one of the critical regulators for HGF-induced anti-oxidative cytoprotective functions in chemotherapeutic agent-treated cancer cells." (PMID 30647407, 2019). "The tight regulation of the HGF-MET signaling that occurs in normal tissues is lost through multiple ways in several cancers." (PMID 31040922, 2019). "The cancer stem cells are induced through activation of hepatocyte growth factor (HGF)/Met/c-Jun-N-terminal kinase (JNK) signaling, and autophagy inhibition by rapamycin prevented HCC growth." (PMID 31652893, 2019). "In patients with cancer, high serum levels of HGF were correlated with increasing neutrophil counts and unresponsiveness to anti-PD-1 checkpoint blockade." (PMID 30669409, 2019). "For example, peri-tumor tissue-sourced fibroblasts secrete various cytokines, including IL-6, CXCL1, CCL2, SCGF-β, CXCL8 and HGF, to recruit cancer stem cells, maintain cancer stemness and promote intrahepatic metastasis of HCC." (PMID 30999932, 2019). "To test the effect of HGF neutralization with antibody on anti-cancer T cell immunity, we generated surrogate antibodies that are reactive to the mouse homologue of the epitope targeted by YYB-101." (PMID 30669409, 2019). "Again, with both cell lines, we have observed that the biotin-conjugated anti-MET antibodies can effectively block HGF-induced cancer cell invasion." (PMID 30760737, 2019). "The HGF/c-MET axis has recently become a therapeutic target for the treatment of various types of cancer." (PMID 31355133, 2019). "Those same authors also demonstrated that many other factors— including IL-6, RANTES, HGF, STAT3—implicated in the control of cancer cell growth and motility and considered targets for anticancer therapies, were downregulated after TARGIT8,44–46." (PMID 31133667, 2019). "During the last three decades, the dysregulation of the HGF/MET pathway has been identified as a common characteristic in different types of human cancer." (PMID 31547040, 2019). "CAF-derived HGF promotes cancer cell tumorigenic and metastatic potential by activating the HGF/c-MET pathway." (PMID 30927908, 2019). "These experiments demonstrate that pre-treatment of anti-MET antibodies can effectively block the subsequent HGF-mediated AXL co-activation in these cancer cells, and such effects can be detected within less an hour following a 7-minute antibody exposure." (PMID 30760737, 2019). "Deregulated HGF-MET signaling is implicated in oncogenesis and therapeutic resistance in several cancers." (PMID 31040922, 2019). "YAP knockdown also led to moderately increased expression of hepatocyte growth factor (HGF), a growth factor that is secreted by PaSC and acts on epithelial and cancer cells regulating angiogenesis, tissue regeneration and cancer cell growth." (PMID 31849712, 2019). "In a second mesenchymal NSCLC cell line (H1792), the HGF neutralizing antibody did reduce basal cMet activation consistent with cancer cell production of HGF leading to cMet activation that has previously been well established in some NSCLC tumors." (PMID 31040125, 2019). "Several studies also report that IL-1 secretion of OSCC cells stimulates TGF-β and HGF production by CAFs, which promotes invasion of cancer cells in vitro." (PMID 30927923, 2019). "As HGF is known to promote malignant progression in tumors and resist anti-cancer drugs because of the cell-protective effect of HGF, all the trials excluded patients with malignant neoplasm." (PMID 31810304, 2019).